FOXP1 (forkhead box P1)
Diseases named in the same sentence as FOXP1 in open-access papers (continued):
Sharing a sentence is not in itself a finding about the gene and the disease.
pituitary (1 paper, 2019). "All these findings suggested that FOXP1-induced CLRN1-AS1 suppressed cell growth in pituitary prolactinoma by acting as a ceRNA to regulate the DKK1/Wnt/β-catenin signaling pathway." (PMID 31235696, 2019). "In summary, this study revealed that FOXP1-induced CLRN1-AS1 regulated cellular functions in pituitary prolactinoma by sponging miR-217 to release the DKK1/Wnt/β-catenin signaling pathway." (PMID 31235696, 2019).
Pleural effusion (1 paper, 2025). The presence of an excessive amount of fluid in the pleural cavity. "Analysis of DEGs in Cycling GZMA and GZMA CD4 T cells from pleural effusion of HP and LCP revealed that seven transcription factors (MLLT3, KLF12, FOXP1, NFKB1, ZEB2, TOX, JAZF1) were upregulated in both cycling GZMA CD4 and GZMA CD4 cells in MPE of LCP." (PMID 40959273, 2025).
Premature ovarian insufficiency (1 paper, 2024). Amenorrhea due to loss of ovarian function before the age of 40. "Silencing FOXP1 results in premature ovarian insufficiency in mice." (PMID 38594460, 2024).
primary cutaneous lymphoma (1 paper, 2023). Cutaneous lymphoma is a heterogeneous entity with respect to its clinical and pathological features, evolutive profile, prognosis, molecular etiology and response to therapy. "Primary cutaneous diffuse large B-cell lymphoma, leg type (PCDLBCL-LT), is a rare and aggressive variant of primary cutaneous lymphoma that typically expresses B cells as well as MUM1/IRF4, BCL2, and FOXP1, whereas BCL6 may be present or undetectable." (PMID 37754668, 2023).
proliferative diabetic retinopathy (1 paper, 2025). Advanced retinopathy due to diabetes mellitus characterized by the formation of new vessels in the retina. "The degraded basement membrane, combined with FOXP1-mediated dysregulation of angiogenic repair mechanisms, provides a permissive environment for abnormal new blood vessel formation characteristic of proliferative diabetic retinopathy." (PMID 41010507, 2025).
Rett syndrome (1 paper, 2014). A severe neurodevelopmental disorder affecting the central nervous system. "Of these, binding sites for the three transcription factors RREB1, FOXP1 and NFY were found in all three genes, suggesting that the three genes implicated in Rett syndrome may be regulated by the same TFs in humans." (PMID 25539566, 2014).
sarcoidosis (1 paper, 2024). Sarcoidosis is a multisystemic disorder of unknown cause characterized by the formation of immune granulomas in involved organs. "Sarcoidosis unique upregulated DEGs in response to LPS were FOXP1 (Forkhead Box P1), DDIT4 (DNA Damage Inducible Transcript 4), and IL7R, and unique downregulated DEGs in sarcoidosis were PYCARD (Caspase Recruitment Domain-Containing Protein 5), CD4, and PLD3 (Phospholipase D Family Member 3)." (PMID 39284999, 2024).
sarcopenia (1 paper, 2023). Progressive decline in muscle mass due to aging which results in decreased functional capacity of muscles. "The comprehensive results show that PDHB plays a sarcoprotective role by suppressing the FoxP1–Arih2 axis and may serve as a therapeutic target in sarcopenia." (PMID 36564038, 2023).
T-cell leukemia (1 paper, 2014). A malignant disease of the T-lymphocytes in the bone marrow, thymus, and/or blood. "RPMI-8402, a T-cell leukemia cell line expressing FOXP1 transcript on low level, was used as control." (PMID 24416450, 2014).
T-cell lymphomas (1 paper, 2015). "Histological evaluation of FOXP1 in T-cell lymphomas has demonstrated that higher FOXP1 expression leads to an improved overall survival in PTCL patients and may be associated with a less activated tumor phenotype." (PMID 26566034, 2015). "However, FOXP1 staining has proven to have disparate results and not all T-cell lymphomas have been found to be immunoreactive to FOXP1." (PMID 26566034, 2015).
thyroid cancer (1 paper, 2022). "Lower FOXP1, FOXP2 and higher FOXP3, FOXP4 levels could be identified in thyroid cancer tissues when compared with matched normal tissue." (PMID 36203616, 2022).
Timothy syndrome (1 paper, 2023). "Similar to the Timothy syndrome mouse model, we found that loss of FOXP1 specifically in iSPNs enhanced the maturation of oligodendrocytes and significantly increased the mature oligodendrocyte marker MOBP in adult striatum." (PMID 37270616, 2023).
trigonocephaly (1 paper, 2018). "Finally, since trigonocephaly has not been previously reported in FOXP1 syndrome, it remains to be proved whether it may be associated with the FOXP1 mutation." (PMID 29330474, 2018).
upper respiratory infections (1 paper, 2021). "Frequent upper respiratory infections during childhood may be related to the role of FOXP1 in transcriptional regulation of B cell development and T cell suppression." (PMID 33892622, 2021).
tumor (161 papers, 2009 to 2026). "FOXP1 haploinsufficiency is identified in development disorders and tumor tissues, these symptoms are similar to that caused by ATR signaling, promoting us to explore the relationship between FOXP1 and ATR signaling." (PMID 39623140, 2025). "Supporting the physiological relevance of this loop, we find pathogenic FOXP1 mutants identified in various tumor tissues with compromised ATR activation and stalled replication fork stability." (PMID 39623140, 2025). "In OC, members such as FOXA1, FOXM1, FOXP4, FOXQ1, and FOXR2 primarily exhibit oncogenic functions, whereas others like FOXO and FOXP1 are associated with tumor-suppressive effects." (PMID 40746724, 2025). "GEPIA assessment of the correlation between expression of the 15 differentially expressed FOXs (DE-FOXs) in the TCGA PAAD data set and the pathological stage of PAAD patients revealed a significant association between FOXK1, FOXQ1, and FOXP1 and tumor stages." (PMID 36622275, 2023). "The function of FOXP1 in PCa has been associated with tumor-suppressor functions through in vitro studies." (PMID 36139541, 2022). "Samples were assessed four months after and revealed that loss of Foxp1 promoted tumor progression by increasing proliferation and expression of Tmprss2." (PMID 36139541, 2022). "Mouse tibialis anterior muscles were therefore injected with AAV9 encoding FoxP1 shRNA or scrambled shRNA 2 weeks before C26 tumour inoculation and tissues were harvested at Institutional Animal Care and Use Committees‐mandated endpoint." (PMID 33527776, 2021). "In ccRCC, FOXP1 expression correlates inversely with tumour grade, and a loss of expression of FOXP1 is associated with a higher expression of ki-67, a relevant index of tumour proliferation." (PMID 33277569, 2020). "In A20 tumors harvested from both experiments immunohistochemical staining confirmed the loss of tumor cell Foxp1 protein expression in vivo in the CRISPR clones." (PMID 32309216, 2020). "miR-149-3p, complementary to the 3′UTRs of mRNAs encoding PD-1, TIM-3, BTLA and Foxp1, was further confirmed to be downregulated in tumour-bearing mouse spleens." (PMID 31594465, 2019). "Accordingly, Foxp1-deficient lymphocytes facilitated enhanced tumor rejection and promoted protection against tumor re-challenge." (PMID 30367168, 2018). "Third, somatic mutations have been reported across a range of human tumor types in several genes within the locus (FOXP1, RYBP, SHQ1)." (PMID 29057879, 2017). "miR-BART11 is reported to cause the dedifferentiation of epithelial cells and tumor-infiltrating macrophages by targeting the cell differentiation-inducing factor Forkhead Box P1 (FOXP1)." (PMID 28757548, 2017). "Increase in miR-9 expression in EGFR mutation bearing cell line leads to tumor suppression via direct regulation of FOXP1." (PMID 28868238, 2017). "We found low FOXP1 expression in four tumor samples with segmental 3p14.1 loss containing the FOXP1 locus, pointing towards haploinsufficiency in these tumors." (PMID 25406647, 2014). "Additionally, xenograft tumor models indicated that FOXP1 deficiency reversed the suppression of subcutaneous tumor growth in nude mice induced by FBXO44 knockdown, and vice versa." (PMID 41051444, 2025). "Moreover, FOXP1 expression was associated with the tumor infiltration of B cells, natural killer cells, and T cells, as well as the cytolytic score across various hematologic malignancies." (PMID 40672953, 2025). "In addition, the high expression of mRNA in the FOXA1, FOXM1, and FOXP1 was significantly associated with tumor stage in BRCA tissues." (PMID 38608123, 2024). "Interestingly, in 50 patients with lung adenocarcinoma, circFoxp1 expression was significantly associated with tumor size, with high circ FOXP1 expression correlating with better prognosis." (PMID 39606233, 2024).
tumor (continued). "In addition, the heatmap for patient P1 shows strong signal that FOXP1 mutates on the trunk of the tumor tree, while BRCA2 has a high probability of having mutated on the trunk of the tree for patient P2." (PMID 36459515, 2022). "Thus, these considerations will lay the foundation of future research and the analysis of the potential applicability of FOXP1 as a target for EBV-associated tumor immunotherapy." (PMID 35165282, 2022). "Hence, the underlying mechanism of FOXO1 or FOXO3 mediated FOXP1/3 expression should be further explored in vitro and in vivo in tumor progression and chemoresistance." (PMID 31815635, 2019). "The R465 and R514 residues are recurrently mutated, with R465G and R514C mutations detected in patients with FOXP1 syndrome, with a characterized clinical symptom of developmental retardation; and R465T, R514C, and R514H mutations in a broad spectrum of tumor tissues as indicated in TCGA database." (PMID 39623140, 2025). "Furthermore, nuclear FOXP1 expression in primary invasive breast carcinoma was positively correlated with nuclear ER-β expression; and this correlation was associated with a low tumor grade and high survival in primary invasive and familial breast cancer." (PMID 25663935, 2015). "This study delineates a previously unrecognized axis of radiation-induced immune evasion in ESCC, revealing that radiotherapy triggers tumor-derived EVs to deliver lncRNA DYNLL1-AS1 that reprograms macrophage PD-L1 expression via SEC22B/FOXP1 signaling." (PMID 41522343, 2026). "To further investigate the effect of FOXP1 expression on the tumor immune microenvironment, we analyzed the relationship between the expression levels of FOXP1 and the immune-related genes." (PMID 40672953, 2025). "Our findings suggested that FOXP1 expression modulated the tumor immune microenvironment by regulating the infiltration of the immune cells in AML, CML, and MM." (PMID 40672953, 2025). "Depending on the cellular context and cancer type, FOXP1 functions as an oncogene or a tumor suppressor." (PMID 40672953, 2025). "Conversely, FOXP1 expression showed a positive correlation with the infiltration of tumor-suppressing immune cells, such as B cells, natural killer (NK) cells, and T cells." (PMID 40672953, 2025). "Estrogens appear to play a central role in modulating the expression and activity of FOXP1 and ERβ, exerting inhibitory effects on tumor proliferation and invasion." (PMID 40746724, 2025). "FoxP1 deletion normalized their diurnal fluctuations in expression, allowing these genes to peak in alignment with natural rest/wake cycles despite tumor burden." (PMID 40349340, 2025). "Silencing FOXP1 reduced the expressions of stemness-associated genes and diminished the formation of both spheroids and colonies, highlighting the crucial role of FOXP1 in regulating stemness in chemoresistant tumor cells." (PMID 40169859, 2025). "The impact of FOXP1 on tumor growth, and progression is controversial because it can act as a tumor suppressor or as an oncogene in different types of cancers." (PMID 40672953, 2025). "FOXP1 is an essential tumor-regulatory molecular that has been widely studied in various cancer types." (PMID 38279090, 2024). "The inhibitory effect of FOXP1 on tumour growth in oesophageal squamous cell carcinoma was experimentally verified." (PMID 38652109, 2024). "Subsequently, in a subcutaneous transplantation tumor model using Foxp1-deficient LLC cells treated with anti-CD47 Ab, it was observed that Foxp1 deletion partially prevented the increase in the CTLA4 level induced by anti-CD47 Ab treatment." (PMID 38398223, 2024). "FOXP1 has the potential to regulate tumour immune infiltrating cells and play a role in anti‐tumour immunity." (PMID 38652109, 2024). "EBV-miR-BART11 and EBV-miR-BART17-3p promote tumor immune escape by inhibiting FOXP1 and PBRM1 and enhancing PD-L1 transcription." (PMID 39015496, 2024).
tumor (continued). "To explore the effect of Foxp1 on the anti-CD47 Ab regulation of the CTLA4 level, we constructed a subcutaneous transplantation tumor model with Foxp1-deleted LLC cells and wild-type LLC cells, respectively, in mice, and treated them with anti-CD47 Ab." (PMID 38398223, 2024). "FOXP1 has different biological effects in different cancers playing a role in promoting or suppressing tumour." (PMID 38652109, 2024). "We assessed changes in the Foxp1 expression levels using IHC in the subcutaneous transplantation tumor model with Foxp1-deleted LLC cells and wild-type LLC cells, respectively." (PMID 38398223, 2024). "Functionally, FOXP1 acts as a tumor suppressor in some solid tumors but also plays oncogenic roles, particularly in hematological malignancies." (PMID 38279090, 2024). "FOXP1 was also reported to act as a tumor suppressor via the negative regulation of the expression of IL-7 in tumor-specific CD4 + T helper cells 7 (Th9)." (PMID 38279090, 2024). "The positive FOXP1 expression was mostly observed in the intrahepatic bile duct epithelium and hepatocytes, and occasionally in the well-differentiated tumor tissues." (PMID 38279090, 2024). "The Foxp1 expression levels were significantly reduced in the Foxp1-deleted tumor model compared to the wild-type tumor model." (PMID 38398223, 2024). "Studies have shown that FOXP1 participates in the occurrence and development of various tumours through different molecular mechanisms." (PMID 38652109, 2024). "In our literature review, we found that genes such as SRSF3, TCF7L2, FOXP1, and CEP55 have been documented to be associated with epithelial-mesenchymal transition (EMT) in tumor cells." (PMID 38254188, 2024). "The experiments such as Cell Counting Kit‐8 (CCK‐8) assay, colony formation assay, and subcutaneous tumour formation assay were conducted to verify the anti‐tumour effect of FOXP1 in oesophageal squamous cell carcinoma and the signalling pathways involved." (PMID 38652109, 2024). "FOXP1 is an important transcription factor of the forkhead box protein family, which has differential expression in various tumour tissues." (PMID 38652109, 2024). "The data showed that the CTLA4 level was reduced in the Foxp1-deleted tumor model compared to the wild-type tumor model." (PMID 38398223, 2024). "Overall, FOXP1 was identified as a newly developed tumor suppressor that exhibits high value in predicting the biological behavior and prognosis of ICC and is a novel possible therapeutic target." (PMID 38279090, 2024). "The high expression of mRNA in FOXA1 (P < .05), FOXM1 (P < .01), and FOXP1 (P < .05) groups was related to tumor stage." (PMID 38608123, 2024). "First, using IHC, we identified that the the Foxp1 level was upregulated in the anti-CD47-treated tumor tissues compared to the control group." (PMID 38398223, 2024). "CircFOXP1 recruits DNMT1 to hypermethylated the promoter of FOXP1, thereby inhibiting the expression of FOXP1, and ultimately facilitating tumor progression in colon cancer." (PMID 38745044, 2024). "In oesophageal squamous cell carcinoma, exosome lncRNA FAM225A upregulates the expression of NETO2 and FOXP1 by absorbing miR‐206, participating in progression and angiogenesis of tumor." (PMID 38652109, 2024). "More experiments are needed to explore the mechanism of FOXP1 regulating tumour immune infiltrating cells." (PMID 38652109, 2024). "The mechanisms of FOXP1-mediated regulation of tumor growth are multilayered and multidirectional, including those associated with tumor immunity, some lncRNAs, and cancer-related signal pathways." (PMID 38279090, 2024). "We further validated the inhibitory effect of FOXP1 on the proliferation of oesophageal squamous cell carcinoma cells in vivo through subcutaneous tumour formation assay." (PMID 38652109, 2024). "We first compared the expression of FOXP1 in various tumours through the GEPIA database, which containing data from TCGA and GTEx programs." (PMID 38652109, 2024).